SUZ12 (SUZ12 polycomb repressive complex 2 subunit)
Diseases named in the same sentence as SUZ12 in open-access papers (continued):
Sharing a sentence is not in itself a finding about the gene and the disease.
glioma (18 papers, 2015 to 2024). A benign or malignant brain and spinal cord tumor that arises from glial cells (astrocytes, oligodendrocytes, ependymal cells). "iRegulon analysis showed GBM-MG crosstalk increased enrichment for SUZ12, previously shown to be increased in high grade astrocytoma and involved in pathways that regulate glioma proliferation and metastasis." (PMID 33208156, 2020). "Both TCGA and CGGA data revealed that the levels of EZH2 and SUZ12 are higher in high-grade glioma." (PMID 39184078, 2024). "SUZ12 is reported to be a tumor suppressor gene in malignant peripheral nerve sheath tumors (MPNSTs) and high-grade gliomas (HGGs), while in epithelial ovarian cancer, breast cancer and other malignancies, it might function to promote oncogenesis." (PMID 32651197, 2020). "Additionally, in the glioma cohort, positive associations between 13-gene scores and REST (rho = 0.39; P < 0.0001) or SUZ12 (rho = 0.17; P < 0.0001) profiles were observed." (PMID 31523055, 2019). "It was revealed that the inhibitory effects of miR-767-5p on glioblastoma cell phenotypes were reversed by overexpression of SUZ12, indicating that the forced upregulation of miR-767-5p may represent a novel therapeutic strategy for glioma patients by targeting SUZ12." (PMID 38473229, 2024). "In renal papillary cell carcinoma, low-grade glioma and hepatocellular carcinoma, poor prognosis was significantly correlated with high expression of all three genes, EZH2, SUZ12, and EED." (PMID 34202528, 2021). "To investigate the relationship between PRC2 components, H3K27me3, and K27M mutant histones in chromatin, we profiled two Polycomb proteins – SUZ12 of the PRC2 complex and the MTF2 transcription factor – in VUMC and in K27M mutant glioma lines." (PMID 32902381, 2020). "We then mapped SUZ12 and MTF2 signal in H3.3K27M glioma cells at sites of K27M enrichment (as H3.1K27M cells only have the K27M epitope dispersed across the genome)." (PMID 32902381, 2020). "miR-105 was reported to serve as tumor-suppressive miRNAs in glioma by targeting SOX9 and SUZ12, as well as in hepatocellular carcinoma by targeting NCOA1." (PMID 29258605, 2017). "PHF19 could form the PRC2 with Ezh2, EED, and SUZ12, knockdown of the PHF19 gene suppressed Ezh2 phosphorylation and proliferation in glioma cells." (PMID 35003347, 2021). "Interestingly, we found that AMPK scores were significantly negatively correlated with TF expression levels in glioma: E2F4 (rho = − 0.48, P < 0.0001), EZH2 (rho = − 0.57, P < 0.0001), FOXM1 (rho = − 0.49, P < 0.0001), SMAD4 (rho = − 0.18, P < 0.0001) and SUZ12 (rho = − 0.23, P < 0.0001)." (PMID 32807122, 2020).
malignant peripheral nerve sheath tumor (17 papers, 2018 to 2025). Malignant peripheral nerve sheath tumor (MPNST) is a rare and often aggressive soft tissue sarcoma occurring in a wide range of anatomical sites. "Loss-of-function mutations in the PRC2 core subunit SUZ12 have been identified in a variety of tumors, including malignant peripheral nerve sheath tumors (MPNSTs)." (PMID 32651197, 2020). "There are evidences that biallelic SUZ12 loss promotes malignant peripheral nerve sheath tumor (MPNST) progression in NF1." (PMID 31652930, 2019). "Patients with microdeletions in the NF1 gene were reported to have a 4-fold increased risk of malignant peripheral nerve sheath tumors (MPNST) and this risk was further increased with codeletion of SUZ12 or EED gene." (PMID 39257551, 2024). "The SUZ12 and EED genes also feature LOF mutations in T-ALL and are particularly frequent in Malignant Peripheral Nerve Sheath tumours (MPNST)." (PMID 36105358, 2022). "Recent studies reported that mutations of SUZ12 and EED had occurred in malignant peripheral nerve sheath tumors as well as head and neck high-grade malignant peripheral nerve sheath tumors had led to the loss of trimethylation at lysine 27 of histone H3 (H3K27me3), a downstream gene of EZH231,32." (PMID 30120321, 2018). "In conjunction with additional tumor suppressors, the PRC2 subunits EED and SUZ12 (but not EZH2) are mutated in 85% of malignant peripheral nerve sheath tumors (MPNST) that develop in patients with NF1 mutations." (PMID 34617019, 2021). "For example, in malignant peripheral nerve sheath tumor, PRC2 is recurrently inactivated through component EED or SUZ12 but not EZH2, despite a complete loss of H3K27me3." (PMID 36612203, 2022).
prostate carcinoma (17 papers, 2013 to 2025). A carcinoma that arises from epithelial cells of the prostate gland. "SUZ12P1 (SUZ12 [suppressor of zeste 12] pseudogene 1) is a pseudogene, which is a long noncoding RNA promoting the proliferation of and inhibiting apoptosis of prostate cancer." (PMID 36575854, 2023). "DNA chromatin remodeling proteins, such as EZH2, SUZ12, and DNMT3a, were also under-expressed, as observed in prostate cancer studies." (PMID 24504051, 2014). "In these experiments, we determined the SUZ12-bound RNA fraction in the human prostate cancer cell line LNCaP upon formaldehyde-fixation (RNA-IP) via next-generation sequencing and compared these results to input material." (PMID 24216986, 2013). "The TF-hub gene network revealed that SUZ12 regulates 12 hub genes and may play a significant role in the development of prostate cancer." (PMID 36497036, 2022). "Noticeably, we established a relationship between the effects of Snail associated with Suz12 regulated by EGFR signaling in Ras-activated prostate cancer, and we have deciphered a novel role of miR-203 in regulating SUZ12 expression in prostate cancer via direct interaction with SUZ12 3'UTR." (PMID 25004126, 2014). "Notably, the auxiliary protein Uhrf1 found in the ‘darkorange’ module has previously been shown to interact with PRC2 members Ezh2 and Suz12 in prostate cancer cells, where elevated UHRF1 levels correlate positively with an increase in EZH2 and were associated with poor clinical outcome." (PMID 25605797, 2015). "Our X2K analysis unveiled heightened expression of EZH2 and SUZ12, core components of the PRC2 complex, in AA prostate cancer." (PMID 40104216, 2025). "Treatment of human prostate cancer cell lines DU145 and 22Rv1, known for high constitutive EZH2 expression, with luteolin significantly reduced EZH2 and suppressor of zeste 12 (SUZ12) protein levels in a dose- and time-dependent manner." (PMID 41226811, 2025). "This parallel underscore the potential significance of epigenetic regulation, particularly involving SUZ12 and EZH2, in contributing to prostate cancer disparities among different racial groups." (PMID 40104216, 2025). "Silibinin treatment of DU145 and PC3 prostate cancer cell lines resulted in a significant reduction in the expression of PRC2 complex members, including EZH2, SUZ12, and EED." (PMID 41226811, 2025). "Subsequent studies of prostate cancer demonstrated that high EZH2 and SUZ12 expression correlate with metastasis progression, and for EZH2high, with poor survival prognosis." (PMID 34202528, 2021). "EZH2, SUZ12, and EED gene amplification was most frequently found in prostate cancer, whereas lymphoid malignancies (DLBCL) frequently showed EZH2 mutations." (PMID 34202528, 2021). "In accordance with tissue origin data, the majority of alterations in the EZH2, SUZ12, and EED genes in prostate cancer are represented by amplifications." (PMID 34202528, 2021). "The expression of Suz12, member of the PRC2, is up-regulated in various cancers such as melanoma, lymphoma, breast, and prostate cancer." (PMID 25004126, 2014). "Furthermore, X2K (eXpression2Kinases) analysis of UP DEGs in AA prostate cancer samples showed enrichment of EZH2 and SUZ12 transcription factors which are elements of PRC2 complex." (PMID 40104216, 2025). "Another miRNA, miR-520a binds to the 3' UTR of target genes including Microtubule Affinity Regulating Kinase 2 (MARK2), Estrogen Receptor 1 (ESR1) at early-stage cancer and Suppressor of Zeste 12 (SUZ12) during advance-stage and ESR1 during CRPC progression of prostate cancer." (PMID 31756185, 2019). "A more recent study analyzing the function of EZH2 in breast and prostate cancer lines has reported that the recruitment of EZH2 and Suz12 (both PRC2 subunits) to the promoter region of the tumor-suppressor gene RKIP is accompanied by H3K27 and H3K9 trimethylation." (PMID 23826629, 2013).
prostate carcinoma (continued). "Finally, in experiments from our own laboratory, we analyzed the binding ability of transcripts over 200 nucleotides in size to SUZ12, one of the PRC2 complex components, in prostate cancer cells." (PMID 24216986, 2013).
colorectal cancer (14 papers, 2014 to 2025). A primary or metastatic malignant neoplasm that affects the colon or rectum. "For example, elevated SUZ12 is significantly associated with tumor size, lymph node metastasis and clinical stages in non-small cell lung cancer and colorectal cancer." (PMID 28228691, 2017). "In conclusion, we showed that combined expression of PcG proteins EZH2, BMI1 and SUZ12 and their associated histone modification H3K27me3 has prognostic value in our colorectal cancer study cohort." (PMID 25243792, 2014). "In search for new biomarkers, we investigated the expression of Polycomb-group (PcG) proteins EZH2, BMI1 and SUZ12 and associated histone modification H3K27me3 in colorectal cancer." (PMID 25243792, 2014). "In this study, we investigated the expression of three PcG proteins (EZH2, BMI1 and SUZ12) and associated histone modification H3K27me3 in colorectal cancer tissues." (PMID 25243792, 2014). "SUZ12 was reported to be an oncogene in colorectal cancer, which plays a cancer-promoting role by methylating histone H3." (PMID 33535181, 2021). "Notably, highly elevated SUZ12 has been found in bladder, gastric, non-small cell lung and colorectal cancer, etc.." (PMID 28228691, 2017). "In order to obtain more information about epigenetic pathways with potential prognostic value in colorectal cancer, we performed multivariate survival analyses using combined expression data of multiple PcG proteins (EZH2, BMI1 and SUZ12) and their associated histone modification H3K27me3." (PMID 25243792, 2014). "Using immunohistochemical staining (IHC) and semi-automated scoring, we studied the expression of PcG proteins EZH2, BMI1 and SUZ12 and their associated histone modification H3K27me3 in a cohort of 247 TNM stage I-III colorectal cancer patients, in correlation with clinical outcome." (PMID 25243792, 2014). "In particular, SUZ12 is reportedly overexpressed in colorectal cancer." (PMID 25334066, 2014). "For these reasons, HOTAIR or SUZ12 might be a treatment target in colorectal cancer." (PMID 25334066, 2014). "The suppressive role of miRNA-487b was also indicated in colorectal cancer via targeting MYC, SUZ12 and KRAS." (PMID 37108073, 2023). "As we expected, RIP results revealed that SNHG1 bound with EZH2, SUZ12 and EED in colorectal cancer cells." (PMID 30266084, 2018). "Besides, through analyzing colorectal cancer RNA sequencing data in TCGA, we found SNHG1 expression was positively correlated with EZH2, SUZ12 and EED." (PMID 30266084, 2018).
neurofibroma (14 papers, 2011 to 2024). An intraneural or extraneural neoplasm arising from nerve tissues and neural sheaths. "To determine if PRC2 inactivation was sufficient for selumetinib resistance, we used CRISPR interference (CRISPRi) to suppress SUZ12 or EED in NF1-mutant NF95.11b neurofibroma cells." (PMID 38216572, 2024). "To verify the role of ADCY1 in SUZ12 mutation, we used RNA interference and plasmid transfection to interfere with SUZ12 expression in plexiform neurofibroma (pNF) and MPNST cell lines and then treated the cells with forskolin, IBMX and H89." (PMID 34692515, 2021). "Whole exome sequencing identified recurrent somatic short variants (SSVs) in the core PRC2 components SUZ12 or EED in Group 1 but not Group 2 or Group 3 histological neurofibromas and MPNSTs." (PMID 38216572, 2024). "These rearrangements lead to a more severe “contiguous gene syndrome” with higher incidence of neurofibromas and MPNSTs, likely attributable to the involvement of tumor suppressor genes in co-deleted regions (e.g., SUZ12—OMIM *606245, RNF135—OMIM *611358, and ADAP2—OMIM *608635)." (PMID 33919865, 2021). "In conclusion, our findings suggested that SUZ12 loss potentiates the effects of NF1 mutations by amplifying Ras signaling through the ADCY1/cAMP/Rap1/ERK pathway and that SUZ12 may serve as a therapeutic and prognostic biomarker in NF1-associated neurofibromas." (PMID 34692515, 2021). "After performing MMP analysis and/or MLPA analysis, we observed that in two neurofibromas (P004-7N, P082-1N) the deletion breakpoints were located very close to the low-copy repeats (NF1-REPs and the SUZ12 sequences) flanking the NF1 gene region." (PMID 21031597, 2011). "Hence, mutually exclusive bi-allelic loss-of-function mutations in the PRC2 core proteins SUZ12 and EED are recurrently observed in NF1-associated MPNSTs, while not observed in the pre-cancerous tumours, neurofibromas." (PMID 38448973, 2024). "Moreover, MPNSTs from NPcis mice did not develop from pre-existing plexiform neurofibromas, which commonly involves progressive loss of CDKN2A and SUZ12 or EED in NF1 patients." (PMID 33669386, 2021). "Importantly, we identified one neurofibroma (P082-1N) bearing a type-2 NF1 deletion, caused by a nonallelic homologous recombination (NAHR) between the SUZ12 gene and its pseudogene, which are both located adjacent to the NF1 low copy repeats." (PMID 21031597, 2011).
endometrial stromal tumor (12 papers, 2010 to 2025). Neoplasms of the endometrial stroma that sometimes involve the myometrium. "It has been reported that JAZF1 is a component of gene fusion with SUZ12, which is found in endometrial stromal tumor." (PMID 24586834, 2014).
colon cancer (10 papers, 2013 to 2023). "The importance of DCAF1 with respect to the observed interaction was further confirmed by the finding that DCAF1 knockdown almost completely abrogates the ability of EZH2 to interact with EED and SUZ12 in colon cancer cells." (PMID 37069142, 2023). "Regions binding the polycomb repressor complex 2 (PRC2) component SUZ12 in ES cells were found to be enriched among the loci differentially methylated between colon cancer and normal colon." (PMID 23324568, 2013). "SUZ12 polycomb repressive complex 2 subunit (SUZ12), another key component of the PRC2 complex, was found to have tumor-promoting functions in several cancers, including colon cancer." (PMID 25243792, 2014). "However, our results did show that the inhibitory effect of 5‐Aza on MYC, SUZ12, and KRAS is at least partially achieved by miR‐487b in colon cancer cells." (PMID 30791232, 2019).
glioblastoma (10 papers, 2015 to 2024). The most malignant astrocytic tumor (WHO grade IV). "TRG-AS1 is high expressed in glioblastoma tissues and cells, is associated with poor prognosis, and stimulates glioblastoma cell proliferation by suppressing the expression of miR-877-5p to dysregulate the expression of SUZ12." (PMID 34136488, 2021). "But in glioblastoma, it serves as a tumour suppressor where its one component SUZ12 actively participates in inhibiting cell proliferation." (PMID 37277696, 2023). "Targeting oncogenic chromatin repressors such as EZH2 (Enhancer of zeste 2 polycomb repressive complex 2 subunit), BMI-1, and SUZ12, the cooperative strategy of these microRNAs disrupts critical survival mechanisms in glioblastoma cells and unveils promising therapeutic avenues." (PMID 38419943, 2024). "The analyses revealed that SATB2, EZH2, SUZ12, and PCL3 are enriched in older patients with glioblastoma (GBM) with worse performance status." (PMID 33124191, 2020).
hepatocellular carcinoma (10 papers, 2010 to 2026). A malignant tumor that arises from hepatocytes. "In contrast to a number of SUZ12 target genes identified in hepatocellular carcinoma and embryonic fibroblast, little knowledge has been obtained about SUZ12 targets in PCa." (PMID 23451058, 2013). "Most SUZ12 targets in hepatocellular carcinoma and embryonic fibroblast, showed little expression change in this dynamic data after DHT stimulation." (PMID 23451058, 2013). "Our study also provided first experimental evidence to show that induction of endogenous miR-101 indeed is accompanied with lower EZH2, EED and SUZ12 level and histone 3 lysine 27 trimethylation in human hepatoma cells." (PMID 20444294, 2010). "Moreover, it has been reported that SUZ12 is correlated with the expression of ZNF198 in hepatic carcinoma, and their interaction promotes the proliferation and invasion of hepatic carcinoma." (PMID 33145980, 2020). "Likely in hepatocellular carcinoma, specific lncRNAs recruit polycomb proteins (EZH2, SUZ12) and histone demethylases (KDM2A) to FGFR2 loci, facilitating exon IIIb inclusion and favoring tumor-suppressive isoform expression." (PMID 41584352, 2026). "In a hepatocellular carcinoma, when originated by the infection of hepatitis B virus (HBV), Plk1 has been suggested to participate in the transformation event by modulating the degradation of two transcription repression factors, SUZ12 and ZNF198." (PMID 30862113, 2019). "Degradation of SUZ12 and ZNF198 is critical for hepatocellular carcinoma appearance and progression, since both proteins are essential subunits of the polycomb repressive complex 2 (PRC2), and the LSD1-CoREST-HDAC1 repression complex respectively, with strong implications in cancer pathogenesis." (PMID 30862113, 2019).
lung cancer (9 papers, 2013 to 2025). A malignant neoplasm involving the lung. "In addition, HDAC1 maintains lung cancer cell stemness and induces a drug-resistant phenotype in lung cancer cells by inhibiting miR-200b expression and reducing the targeting of miR-200b to Suz12." (PMID 37144123, 2023). "EZH2 and SUZ12, the components of PRC2, have been found to overexpress in a lot of human cancers, including lung cancer." (PMID 24155936, 2013). "A previous study has reported that MYC, SUZ12, and KRAS are the biotargets of miR‐487b in cigarette smoke‐induced lung cancer, leading us to speculate that miR‐487b could also suppress CRC tumorigenesis by inhibiting these three genes." (PMID 30791232, 2019).